ZHX1 (zinc fingers and homeoboxes 1)
Description:
Acts as a transcriptional repressor. Increases DNMT3B-mediated repressive transcriptional activity when DNMT3B is tethered to DNA. May link molecule between DNMT3B and other co-repressor proteins.
Tractability: PROTAC: UniProt records ubiquitination sites on it; ubiquitination databases record sites on it; its protein half-life has been measured.
Gene: Protein-coding gene on chromosome 8 (123,248,451 to 123,275,541, reverse strand). Ensembl gene ENSG00000165156.
Subcellular location: Nucleus
Subcellular location (Human Protein Atlas): Nucleoplasm
Gene Ontology:
Molecular function: DNA-binding transcription factor activity; protein binding; protein heterodimerization activity; DNA-binding transcription factor activity, RNA polymerase II-specific; DNA binding
Biological process: negative regulation of DNA-templated transcription; negative regulation of transcription by RNA polymerase II; regulation of transcription by RNA polymerase II
Cellular component: nucleoplasm; nucleus; chromatin
Genetic constraint (gnomAD): Loss-of-function variants: 20 observed, 65.02 expected, observed/expected ratio (o/e) 0.31, 90% interval 0.22 to 0.45. The upper end of that interval is the gene's LOEUF score, 0.45, which puts it in group 1 of 6, group 1 being the genes least tolerant of losing a copy. Missense variants: 800 observed, 1,092.5 expected, observed/expected ratio (o/e) 0.73, 90% interval 0.69 to 0.78. Synonymous variants: 318 observed, 374.04 expected, observed/expected ratio (o/e) 0.85, 90% interval 0.77 to 0.93.
Homologues: Orthologues: macaque ZHX1 (99% identical), chimpanzee ZHX1 (97% identical), dog ZHX1 (96% identical), rabbit ZHX1 (96% identical), pig ZHX1 (95% identical), rat Zhx1 (93% identical), mouse Zhx1 (91% identical), tropical clawed frog zhx1 (67% identical). Paralogues in human: ZHX2 (36% identical), ZHX3 (34% identical), HOMEZ (13% identical).
Diseases named in the same sentence as ZHX1 in open-access papers:
ZHX1 is named in the same sentence as 23 diseases in open-access papers, as found by Europe PMC text mining. Sharing a sentence is not in itself a finding about the gene and the disease. The quoted sentences say what the papers report.
gastric cancer (11 papers, 2016 to 2025). A primary or metastatic malignant neoplasm involving the stomach. "A more recent study indicated that an increased ZHX1 expression was associated with a better or worse prognosis for patients with gastric cancer in the clinical stages, including lymph node metastasis or distant metastasis, and surgical therapy." (PMID 36232466, 2022). "For example, ZHX1, a unique transcription factor in M-AD, has been implicated in gastric cancer, chronic lymphocytic leukemia, and gliomas." (PMID 36389068, 2022). "For example, the reduced ZHX1 expression was associated with TNM stage progression in gastric cancer, and a reduction in nuclear ZHX2 expression was associated with short survival in HCC." (PMID 28152006, 2017). "As a transcription repressor, ZHX1 has been associated with the progressions of cholangiocarcinoma, hepatocellular carcinoma, gastric cancer, and breast cancer." (PMID 29207666, 2017). "We recently showed that high ZHX1 expression predicts an unfavorable OS rate in breast cancer but presents favorable OS for gastric cancer, confirming its different roles in different cancer types." (PMID 41480542, 2025). "While, in gastric carcinoma cells, miR-199a-3p targeted zinc fingers and homeoboxes 1 (ZHX1), resulting in the proliferation of gastric tumor cells and inhibition of apoptosis." (PMID 39125630, 2024). "In cultured gastric cancer cells, stable transfection with plasmids overexpressing ZHX1 significantly promoted apoptosis, and inhibited cell proliferation and migration." (PMID 36232466, 2022). "In contrast, ZHX1 exerts tumor-suppressive functions in gastric cancer, in which ZHX1 expression was reduced." (PMID 36232466, 2022). "that ZHX1 was downregulated in gastric cancer tissues and inhibited gastric cancer cell growth via induction of cell-cycle arrest and apoptosis." (PMID 31648104, 2019). "In hepatocellular carcinoma and gastric cancer, the expression of ZHX1 was lower than in normal tissues, and the nuclear expression of ZHX2 was diminished in HCC." (PMID 28152006, 2017). "ZHX1 has been reported to induce apoptosis and cell cycle arrest (G1/S) by regulating cyclin D1, cyclin E, Bcl2, Bax, and cleaved caspase-3 in gastric cancer, and ZHX2 overexpression was correlated with low expressions of cyclin A and cyclin E in HCC." (PMID 28152006, 2017). "ZHX1 has been shown to decrease the proliferation and migration of gastric cancer cells, and its overexpression has been reported to reduce hepatocarcinoma cell proliferation (SMMC-7721 cells)." (PMID 27835650, 2016). "Zinc-fingers and homeoboxes 1 (ZHX1) is a transcription repressor that has been associated with the progressions of hepatocellular carcinoma, gastric cancer, and breast cancer." (PMID 27835650, 2016). "In silico analysis showed that ZHX1 is amplified in many cancers, including breast cancer, gastric cancer, and CCA." (PMID 27835650, 2016). "In the present study, the ZHX1 gene was amplified in various cancer cells, including breast cancer, gastric cancer, and CCA." (PMID 27835650, 2016). "The study also demonstrated that miR-199a-3p could negatively regulate ZHX1 gene expression in gastric cancer cells." (PMID 36232466, 2022). "In gastric cancer, miR-199a-3p inhibits cancer progression by targeting oncogenic ZHX1." (PMID 31718630, 2019). "Reconstitution of ZHX1 expression abrogates gastric cancer oncogenicity." (PMID 27411336, 2016). "Furthermore, it was recently reported ZHX1 inhibited gastric cancer cell proliferation, and that ectopic ZHX1 expression decreased proliferation of SMMC-7721 cells (a hepatocellular carcinoma cell line)." (PMID 27835650, 2016). "ZHX1 overexpression inhibited the proliferation of hepatocellular carcinoma (HCC) cells and its downregulation increased the proliferation of gastric cancer cells." (PMID 28152006, 2017).
gastric cancer (continued). "Zinc-fingers and homeoboxes-1 (ZHX1), which contains two C2H2 zinc finger motifs and five homeodomains, has been reported to be down-regulated in hepatocellular carcinoma and gastric cancer." (PMID 27411336, 2016).
glioblastoma (8 papers, 2019 to 2023). The most malignant astrocytic tumor (WHO grade IV). "While Zhx1 inhibited the apoptosis of glioblastoma cells by regulating the expression of Bcl2 and Bax and induced early proteinuria and primary glomerular disease by upregulating the Angptl4 expression." (PMID 37452012, 2023). "Zhx1 promoted the proliferation, migration, and invasion of glioblastoma cells and cholangiocarcinoma cells by activating the transcription of the EMT genes Snail2 and Twist1 or enhancing the Egr1 expression, respectively." (PMID 37452012, 2023). "In vitro, the knockdown of ZHX1 expression suppressed cell proliferation, mobility, migration, and invasion in glioblastoma." (PMID 36232466, 2022). "In vitro and in vivo studies have shown that LncRNA MALAT1 facilitates glioblastoma cell proliferation and progression by reducing miR-199a to promote ZHX1 expression." (PMID 36232466, 2022). "In glioblastoma, the messenger RNA and protein expression of ZHX1 are increased compared with normal brain tissue, and ZHX1 overexpression was associated with short overall survival." (PMID 36232466, 2022). "Accordingly, MALAT1 expression enhanced tumor proliferation by upregulating Rap1b and zinc-fingers and homeoboxes 1 (ZHX1) by sponging miR-101 in glioma and miR-199a in glioblastoma, respectively." (PMID 34322395, 2021). "For example, lncRNA MALAT1/miR-199a/ZHX1 axis suppresses glioblastoma proliferation and progression, and lncRNA-DLEU2/miR-186-5p/PDK3 axis advances glioma cell progression." (PMID 34459789, 2021). "For example, MALAT1 regulated cisplatin resistance through the miR-101-3p/VEGF-C axis in bladder cancer and the hindering of MALAT1/miR-199a/ZHX1 axis suppressed the progression of glioblastoma." (PMID 31953613, 2020). "The complex formed by MALAT1/miR-199a/ZHX1 promotes glioblastoma cell proliferation in vitro and in vivo, and correlates with glioblastoma progression in patients." (PMID 32283739, 2020). "The functional role and regulating mechanism of ZHX1 has not been elucidated in glioblastoma (GBM)." (PMID 31648104, 2019).
glioma (8 papers, 2019 to 2023). A benign or malignant brain and spinal cord tumor that arises from glial cells (astrocytes, oligodendrocytes, ependymal cells). "Another study on glioma also showed that ZHX1 is an oncogene, and it was identified as a target gene of miR-23b-3p." (PMID 36232466, 2022). "LncRNA SNHG17 can absorb miR-23b-3p like a sponge to elevate ZHX1expression; therefore, increased SNHG17 and ZHX1 expressions and the reduced miR-23b-3p expression were found in glioma tissues." (PMID 36232466, 2022). "The lncRNA SNHG17 also promotes the progression of glioma cells by regulating the miR-23b-3p/ZHX1 axis." (PMID 34101736, 2021). "In our study, we found that ZHX1 similarly exerted a regulator role on glioma cell apoptosis and promoted glioma cell survival via upregulation of Bcl-2 and downregulation of Bax." (PMID 31648104, 2019). "Analysis of the tissue microarray data from the GEO database (GEO: GSE68848) demonstrated that the ZHX1 mRNA level in glioma tissue was significantly higher compared to normal brain tissues." (PMID 31648104, 2019). "We analyzed the expression of the MALAT1/miR-199a/ZHX1 axis and its correlation with patients’ overall survival using two different glioma gene-expression datasets." (PMID 31648104, 2019). "In addition, lncRNA LINC01140 promote the development of glioma by downregulating miR-199a-3p expression and indirectly upregulating ZHX1 expression." (PMID 36232466, 2022). "Another work showed LINC01140 could promote glioma progression via regulating miR-199a-3p/ZHX1 axis." (PMID 33613672, 2021). "Considering miR-199a’s role in the carcinogenesis of glioma and its potential regulatory effect on ZHX1, we conducted a bioinformatics analysis, which predicted a binding interaction between miR-199a and MALAT1 (metastasis-associated lung adenocarcinoma transcript-1), a lncRNA." (PMID 31648104, 2019). "The zinc-fingers and homeoboxes 1 (Zhx1), upregulated by the lncRNA-MALAT1/miR-199a axis, promoted glioma cell proliferation and progression." (PMID 37452012, 2023). "Further, ZHX1 protein expression levels were significantly higher in high-grade glioma (WHO grade IV) and low-grade glioma (WHO grade II) tissues, compared to the normal brain tissue." (PMID 31648104, 2019). "To investigate the role of MALAT1 in regulating ZHX1 expression, we knocked down MALAT1 in glioma cell lines with short hairpin RNAs (shRNAs)." (PMID 31648104, 2019).
hepatocellular carcinoma (6 papers, 2016 to 2022). A malignant tumor that arises from hepatocytes. "ZHX1 expression has been reported to be decreased in hepatocellular carcinoma tissues." (PMID 27835650, 2016). "that demonstrated markedly reduced ZHX1 expression levels in human hepatocellular carcinoma (HCC) tissues and significantly reduced HCC cell proliferation with increased ZHX1 expression." (PMID 31648104, 2019). "In hepatocellular carcinoma (HCC), ZHX1 has also been reported as a tumor suppressor." (PMID 36232466, 2022).
cholangiocarcinoma (5 papers, 2016 to 2023). A carcinoma that arises from the intrahepatic biliary tree (intrahepatic cholangiocarcinoma) or from the junction, or adjacent to the junction, of the right and left hepatic ducts (hilar cholangiocarcinoma). "Immunohistochemical staining analysis revealed that ZHX1 is amplified and overexpressed in cholangiocarcinoma tissues." (PMID 36232466, 2022). "In vitro studies showed that overexpressing ZHX1 facilitated cholangiocarcinoma cell proliferation, migration, and invasion." (PMID 36232466, 2022). "In summary, we found ZHX1 was found to play essential roles in the proliferation, migration, and invasion of cholangiocarcinoma cells, and that its effect on the proliferation was mediated partially through EGR1." (PMID 27835650, 2016). "The present study also provides evidence ZHX1 positively regulates the motility and invasiveness of cholangiocarcinoma cells." (PMID 27835650, 2016). "Similarly, in the present study, ZHX1 knockdown reduced and its overexpression increased cell proliferation in cholangiocarcinoma cell lines." (PMID 27835650, 2016). "All results for effects of ZHX1 on cholangiocarcinoma cells were summarized as a table." (PMID 27835650, 2016). "However, the functional roles of ZHX1 in cholangiocarcinoma (CCA) have not been determined." (PMID 27835650, 2016).
breast carcinoma (4 papers, 2016 to 2025). "Consistent with our results, in non-metastatic human breast cancer cells, ZHX1 expression was reduced by Pea3 knockdown, and this led to decreases in invasiveness and metastasis." (PMID 27835650, 2016). "For example, lncRNA LINC00899 suppresses breast cancer progression by inhibiting miR-425, lncRNA ZFAS1 regulates oesophageal squamous cell carcinoma cell malignant behaviours via the miR-124/STAT3 axis and lncRNA MALAT1 promotes GBM proliferation and progression by targeting the miR-199a/ZHX1 axis." (PMID 33832517, 2021).
cervical cancer (3 papers, 2020 to 2022). A primary or metastatic malignant neoplasm involving the cervix. "Another study has demonstrated the oncogenic roles of lncRNA DLG1-AS1/miR-107/ZHX1 axis in cervical cancer." (PMID 36232466, 2022). "DLG1-AS1, a novel lncRNA, was reported to promote the proliferation of cervical cancer cells by competitively binding to miR-107 and upregulating the expression of ZHX1." (PMID 33197895, 2020). "However, it has also been reported that lncRNA DLG1-AS1 can promote the proliferation of cervical cancer cells by competitive binding with miR-107 and up-regulating the expression of ZHX1." (PMID 31768842, 2020). "Vice versa, increasing the expression of miR-107 rescued the role of DLG1-AS1 in cervical cancer cell proliferation, indicating that the oncogenic effects of DLG-AS in cervical cancer are miR-107/ZHX1-dependent." (PMID 36232466, 2022).
chronic lymphocytic leukemia (3 papers, 2021 to 2022). "The prognostic impact of ZHX1 and ZHX2 in chronic lymphocytic leukemia (CLL) has recently been reported." (PMID 36232466, 2022).
Hodgkins lymphoma (2 papers, 2016 to 2022). A heterogeneous group of malignant lymphoid neoplasms of B-cell origin characterized histologically by the presence of Hodgkin and Reed-Sternberg (HRS) cells in the vast majority of cases. "In addition, in Hodgkin’s lymphoma, ZHX1 was found to inhibit B-cell differentiation and to be associated with the pathogenesis of lymphoid malignancy." (PMID 27835650, 2016). "Lastly, the Hodgkin lymphoma cell lines that showed no expression of orthodenticle homeobox 1 and 2 (OTX1/2) (e.g., OTX 1 and 2 negative) overexpressed ZHX1, correlating with the genomic amplification of the 8q24 locus, supporting the oncogenic potential of ZHX1 in Hodgkin lymphoma." (PMID 36232466, 2022).
lung carcinoma (2 papers, 2017 to 2025). "In the present study, a significant association was observed between ZHX1 mRNA expression and survival outcomes in patients with lung cancer in this study." (PMID 41480542, 2025). "Increased ZHX1 mRNA expression was found to be associated with a better OS rate in patients with lung cancer." (PMID 41480542, 2025). "For example, ZHX1 expression was inversely related with those of USF-2 and VEGF-B, which have been associated with the proliferation of lung cancer cells and endothelial cell migration, respectively." (PMID 28152006, 2017). "Of note, high ZHX1 levels displayed an improved PPS rate in patients with lung cancer." (PMID 41480542, 2025). "Additionally, analysis from the CCLE database demonstrated that the mRNA levels of ZHX1, ZHX2 and ZHX3 in lung cancer cell listed in the 19th, 25th, and 10th highest positions across all types of cancer, respectively." (PMID 41480542, 2025).
clear cell renal carcinoma (1 paper, 2022). A malignant epithelial neoplasm of the kidney characterized by the presence of lipid-containing clear cells within a vascular network. "A study on clear cell renal cancers (ccRCC) based on an online database showed that both ZHX1 and ZHX3 expression levels were downregulated, while ZHX2 was upregulated." (PMID 36232466, 2022).
glomerular disease (1 paper, 2023). "Previous studies showed that Zhx1 was involved in carcinogenesis and glomerular disease by targeting specific genes." (PMID 37452012, 2023).
lung adenocarcinoma (1 paper, 2025). A carcinoma that arises from the lung and is characterized by the presence of malignant glandular epithelial cells. "Except the comparison of ZHX1 on lung squamous cell carcinoma (LUSC), the mRNA levels of all three ZHX factors was significantly lower in both lung adenocarcinoma (LUAD) and LUSC tissues than in normal tissues." (PMID 41480542, 2025).
lymph node metastasis (1 paper, 2022). "As seen with ZHX1, ZHX3 showed a lower expression in cancers, and was associated with a high-risk of lymph node metastasis and worse outcomes." (PMID 36232466, 2022). "For instance, a lower ZHX1 expression was related to a better prognosis of patients without lymph node metastasis, whereas a higher ZHX1 expression was related to a better prognosis of patients without distant metastasis." (PMID 36232466, 2022).
ovarian carcinoma (1 paper, 2016). A malignant neoplasm originating from the surface ovarian epithelium. "Here, we report for the first time ZHX1 promotes the proliferation, migration, and invasion of CCA cells, and that it upregulates EGR1, which has been previously shown to promote progression of various cancers including prostate and ovarian cancer." (PMID 27835650, 2016).